RPS10 (ribosomal protein S10)
Description:
Component of the 40S ribosomal subunit. The ribosome is a large ribonucleoprotein complex responsible for the synthesis of proteins in the cell.
Synonyms: MGC88819; S10; eS10; DBA9
Tractability: Small molecule: an approved drug acts on it; a structure with a bound ligand is known; a high-quality ligand is known. PROTAC: UniProt records ubiquitination sites on it; ubiquitination databases record sites on it; its protein half-life has been measured; a small molecule that binds it is known. Other modalities: a drug acting on it is in phase 2 or 3 trials.
Target class: Other cytosolic protein
Gene: Protein-coding gene on chromosome 6 (34,417,447 to 34,426,237, reverse strand). Ensembl gene ENSG00000124614.
Subcellular location: Cytoplasm; Nucleus, nucleolus
Subcellular location (Human Protein Atlas): Cytosol
Pathways (Reactome):
Metabolism of proteins: Eukaryotic Translation Termination; Formation of a pool of free 40S subunits; Formation of the ternary complex, and subsequently, the 43S complex; GTP hydrolysis and joining of the 60S ribosomal subunit; L13a-mediated translational silencing of Ceruloplasmin expression; PELO:HBS1L and ABCE1 dissociate a ribosome on a non-stop mRNA; Peptide chain elongation; Ribosomal scanning and start codon recognition; SRP-dependent cotranslational protein targeting to membrane; Translation initiation complex formation; ZNF598 and the Ribosome-associated Quality Trigger (RQT) complex dissociate a ribosome stalled on a no-go mRNA
Disease: SARS-CoV-1 modulates host translation machinery; SARS-CoV-2 modulates host translation machinery; Viral mRNA Translation
Metabolism of RNA: Major pathway of rRNA processing in the nucleolus and cytosol; Nonsense Mediated Decay (NMD) enhanced by the Exon Junction Complex (EJC); Nonsense Mediated Decay (NMD) independent of the Exon Junction Complex (EJC)
Cellular responses to stimuli: Response of EIF2AK4 (GCN2) to amino acid deficiency
Developmental Biology: Regulation of expression of SLITs and ROBOs
Metabolism: Selenocysteine synthesis
Gene Ontology:
Molecular function: protein binding; RNA binding; structural constituent of ribosome
Biological process: cytoplasmic translation; translation
Cellular component: cytoplasm; cytosolic ribosome; cytosolic small ribosomal subunit; focal adhesion; membrane; nucleolus; cytosol; nucleoplasm; ribosome; synapse
Genetic constraint (gnomAD): Loss-of-function variants: 2 observed, 23.75 expected, observed/expected ratio (o/e) 0.0842, 90% interval 0.033 to 0.26. The upper end of that interval is the gene's LOEUF score, 0.26, which puts it in group 1 of 6, group 1 being the genes least tolerant of losing a copy. Missense variants: 137 observed, 227.12 expected, observed/expected ratio (o/e) 0.6, 90% interval 0.52 to 0.69. Synonymous variants: 70 observed, 78.11 expected, observed/expected ratio (o/e) 0.9, 90% interval 0.74 to 1.09.
Gene-disease validity (ClinGen):
ClinGen rates the evidence that RPS10 causes each of these diseases.
Diamond-Blackfan anemia (autosomal dominant): Definitive. A congenital aregenerative and often macrocytic anemia with erythroblastopenia.
Homologues: Orthologues: rabbit RPS10 (100% identical), tropical clawed frog rps10 (97% identical), chimpanzee RPS10 (92% identical), zebrafish rps10 (92% identical).
Diseases named in the same sentence as RPS10 in open-access papers:
RPS10 is named in the same sentence as 33 diseases in open-access papers, as found by Europe PMC text mining. Sharing a sentence is not in itself a finding about the gene and the disease. The quoted sentences say what the papers report.
Diamond-Blackfan anemia (9 papers, 2012 to 2024). "Further, mutations in several ribosomal protein (RP) genes, such as RPS19, RPL5, RPL11, RPL35A, RPS10, RPS17, and RPS24, cause Diamond-Blackfan anemia (DBA)." (PMID 38820160, 2024). "Mutations in RPS19, RPS28, RPS10 and RPS5 result in the ribosomopathy Diamond-Blackfan anaemia." (PMID 34283226, 2022). "For instance, studies in Diamond-Blackfan anemia (DBA) demonstrated that mutations in 60S or 40S ribosomal proteins [such as RPL5, RPL11, RPS7, RPS10 among others] decrease the ribosome levels but leave the composition of the ribosomes intact." (PMID 30697227, 2018). "In humans, mutations in RPs have been implicated in hematopoetic disorders, most notably Diamond-Blackfan anemia (DBA), which has been attributed to mutations in RPS19, RPS26, RPS24, RPS17, RPS10, RPS7, RPL35a, RPL26, RPL11, and RPL5." (PMID 23382688, 2013).
viral infection (3 papers, 2021 to 2025). "Our study underscores 1Ais as effective means to study the role of eIF1A and RPS10 in translation and suggests their targeted inhibition as potential therapies for cancer and viral infections." (PMID 40355559, 2025). "Regarding proteomics in patients with PHN, some upregulated proteins (HNRNPK and RPS10) were related to viral infection and replication." (PMID 36277496, 2022).
breast carcinoma (2 papers, 2021 to 2024). "In one study, it was shown that LTV1 was substoichiometric in breast cancer cells, producing reduced RPS10 and RACK1 ribosomes." (PMID 34923969, 2021).
sarcopenia (2 papers, 2022 to 2024). Progressive decline in muscle mass due to aging which results in decreased functional capacity of muscles. "A genome-wide association study on Korean cohorts showed that ribosomal protein S10 (RPS10), nudix hydrolase 3 (NUDT3), and glycerol-3-phosphate dehydrogenase 1 like (GPD1L) are genetic biomarkers of age-related sarcopenia." (PMID 39457696, 2024). "The eQTL analysis for muscle mass using GTEx datasets showed that RPS10, NUDT3, NCF2, SMG7, and ARPC5 were differentially expressed in the muscle tissue for sarcopenia." (PMID 35241739, 2022). "Our study identified RPS10, NUDT3, and GPD1L as significant genetic biomarkers for sarcopenia." (PMID 35241739, 2022).
schizophrenia (2 papers, 2023 to 2026). A major psychotic disorder characterized by abnormalities in the perception or expression of reality. "Targets were next examined in the adult rodent (postnatal day70) brain, and a subgroup of these genes (i.e., Furin, Rps10, and Rccd1) were increased concomitant with schizophrenia-like behavior (e.g., decreased pre-pulse inhibition)." (PMID 40827685, 2026). "Placentae from ∆9-tetrahydrocannabinol-exposed males and females revealed altered expression of genes previously identified in human transcriptomic datasets of schizophrenia (i.e., Furin, Rccd1, and Atp5mk), with some expression changes being sex-specific (i.e., Eif5, Rps10, Vps33b, and Iqgap1)." (PMID 40827685, 2026).
cerebrovascular disease (1 paper, 2022). "RPS10 was additionally connected to comorbidities such as COPD, cerebrovascular disease, and renal failure." (PMID 35903362, 2022).
congenital malformations (1 paper, 2020). "Furthermore, global deficiency in RPS10 and RPL26 genes is associated with growth retardation and congenital malformations." (PMID 33324640, 2020).
developmental delays (1 paper, 2025). "However, in gcn-1(n4857) mutants, rps-10 RNAi did not exacerbate the decrease in oxygen consumption (right plot, P = 0.5, paired Student’s t test), despite causing developmental delays, thereby validating the effective knockdown of rps-10." (PMID 39786340, 2025).
diabetic retinopathy (1 paper, 2024). "RPS10 expression levels are related to HbA1c levels and diabetic retinopathy status." (PMID 39916961, 2024).
fibrosarcoma (1 paper, 2018). A malignant mesenchymal fibroblastic neoplasm affecting the soft tissue and bone. "The spectrum of PRMT5 target proteins is not limited to nuclear transcription factors, but also includes cytoplasmic proteins such as golgin, ribosomal protein S10 (RPS10), and rapidly accelerated fibrosarcoma (RAF) protein kinase." (PMID 30613353, 2018).
glioblastoma (1 paper, 2022). The most malignant astrocytic tumor (WHO grade IV). "Eight genes associated with glioblastoma prognosis were identified based on LASSO analysis: RPS10, RPS11, RPS19, RSL24D1, RPL39L, EIF3E, NUDT5, and RPF1." (PMID 36733371, 2022). "From the analysis conducted in this study, it is clear that most of the genes associated with glioblastoma prognosis are ribosomal protein genes, represented by RPS10 and RPS11." (PMID 36733371, 2022). "Eight genes—RPS10, RPS11, RPS19, RSL24D1, RPL39L, EIF3E, NUDT5, and RPF—were found to have an expression in the prognosis of glioblastoma." (PMID 36733371, 2022).
glioma (1 paper, 2020). A benign or malignant brain and spinal cord tumor that arises from glial cells (astrocytes, oligodendrocytes, ependymal cells). "Interestingly, glioma cancer cells have reduced levels of LTV1 and produce ribosomes lacking RPS3, RPS10, and RACK1." (PMID 33334055, 2020).
Intellectual disability (1 paper, 2025). "We prioritized these four RP genes due to their involvement in human ribosomopathies, with rpl-5, rpl-33, and rps-10 relating to DBA, and rps-23 relating to microcephaly and intellectual disability without the blood phenotypes." (PMID 39786340, 2025).
leukemia (1 paper, 2025). A malignant (clonal) hematologic disorder, involving hematopoietic stem cells and characterized by the presence of primitive or atypical myeloid or lymphoid cells in the bone marrow and the blood. "We used K562 leukemia cell line to examine the impacts of reduced levels of specific RP transcripts, RPS10, RPL35A (the ortholog of C. elegans rpl-33), RPL5, and RPS23." (PMID 39786340, 2025). "In human leukemia cells, we also observe a significant reduction in mitochondrial activity and overall energy levels only when RPS10 transcripts are reduced by 50%." (PMID 39786340, 2025).
lupus (1 paper, 2014). "Autoantibodies to 40S ribosomal protein S10, which is also important in protein synthesis, have been detected in 11-40% of lupus patients." (PMID 24908187, 2014).
lymph node metastasis (1 paper, 2024). "Among the aberrantly expressed ribosomal proteins in LSCC tissues with lymph node metastasis, RPS10 and RPL24 are significantly prominent and are considered biomarkers for lymph node metastasis." (PMID 38787142, 2024).
lymphoma (1 paper, 2013). A malignant (clonal) proliferation of B- lymphocytes or T- lymphocytes which involves the lymph nodes, bone marrow and/or extranodal sites. "The relative mRNA expression levels of 4 ribosomal protein genes that were up-regulated in CUP (RPS7, RPL11, RPS10, and RPL36) were compared with the levels in normal lymphoma and 24 known cancer types." (PMID 23671674, 2013).
Obesity (1 paper, 2016). Accumulation of substantial excess body fat. "The genes found to be positively selected in Enshi pigs are involved in crucial biological processes such as body size and immunity (RPS10 and VASN), obesity (GSK3), male fertility (INSL6), and early development (TBX19)." (PMID 27808243, 2016).
Stroke (1 paper, 2025). Sudden impairment of blood flow to a part of the brain due to occlusion or rupture of an artery to the brain. "At the same time, HBB levels stayed high, although PSA samples from stroke patients showed significantly lower levels of LCN2, LAIR2, and RPS10." (PMID 40270596, 2025). "In particular, the three DElncRNAs (CTD-2545M3.2, RP11-24N18.1, and RP11-473C18.7) and four DEGs (LCN2, LAIR2, RPS10, and HBB) that showed the most significant variations between PSA and HC samples were selected for further qPCR verification in the samples from the HC, stroke, PSA, and PSA-T groups." (PMID 40270596, 2025).
systemic candidiasis (1 paper, 2011). "Isogenic wild-type (JC806), crr1Δ (JC566), and reintegrant crr1Δ+CRR1 (JC803) strains, which all express URA3 from the RPS10 locus, were tested in the murine model of systemic candidiasis." (PMID 22164221, 2011).
cancer (11 papers, 2008 to 2025). A tumor composed of atypical neoplastic, often pleomorphic cells that invade other tissues. "The eukaryotic translation initiation factor eIF1A is frequently mutated in cancer and binds the 40S ribosome via a direct interaction with the RPS10 protein." (PMID 40355559, 2025). "It was identified as being useful in detecting PCa within the EV fraction with RPS10 expression levels decreased in cancer." (PMID 36765747, 2023). "In LLC cell-bearing mice, intake of morin prevented the reduction of muscle wet weight and myofiber size by suppressing cancer growth via binding to the ribosomal protein S10 (RPS10)." (PMID 34443483, 2021). "Three of these antigens are encoded by unknown genes (Pr3, Pr6 and Pr Pr52 respectively); additionally three of them (Pr8-ribosomal protein L27a, Pr16-MTA1 and Pr31-ribosomal protein S10) have previously been reported to be over-expressed in cancer." (PMID 18949081, 2008).
infection (4 papers, 2011 to 2025). The state of being infected such as from the introduction of a foreign agent such as serum, vaccine, antigenic substance or organism. "Furthermore, inhibition of RPS10, but not eIF1A, modulates a context-dependent regulatory translation initiation at CUG codon of SARS-CoV-2 and impedes infection." (PMID 40355559, 2025).
tumor (4 papers, 2012 to 2024). "To address any potential bias in protein quantification due to variations in tumor purity, we conducted immunohistochemical (IHC) analyses for RPS10 and RPL24, which were consistent with our Western blot results." (PMID 38787142, 2024).
immune disorders (1 paper, 2024). "Additionally, phagosomes were implicated in certain immune disorders, with RPS4Y1, RPS10, SRRM1, and PNN target genes playing roles in the NOD-like receptor signaling pathway." (PMID 38770048, 2024).
RPS10 also shares sentences with these, for which no sentence is quoted: prostate carcinoma (2 papers); anemia (1); bone marrow failure (1); bone marrow failure syndrome (1); colorectal cancer (1); lung adenocarcinoma (1); lung carcinoma (1); microcephaly (1); renal failure (1).